IL1B (interleukin 1 beta)
Diseases named in the same sentence as IL1B in open-access papers (continued):
Sharing a sentence is not in itself a finding about the gene and the disease.
infection (continued). "Notably, IL-1β levels in the mAb 8E6 treatment group were significantly reduced 24 h post-infection (p = 0.044)." (PMID 39460288, 2024). "The cytokine expression of TNF-α and IL-1β was significantly reduced at 12 h and 24 h post infection of cells treated with LPS isolated from JOL2943, whereas in Hela cells, LPS isolated from JOL2943 induced significantly low TNF-α at 24 hpi and IL-1 at 12 h and 24 hpi." (PMID 38474006, 2024). "Moreover, increased expression of genes encoding for the pro-inflammatory cytokines TNF, IL-1β, and IFN-γ was detected in heart samples obtained from the infected group compared to uninfected controls 6 or 12 months after infection." (PMID 39136016, 2024). "By analyzing circulating blood from naïve and infected mice, we found that loss of IL-1β does not affect circulating neutrophil levels during steady state, but rather prevents neutrophil recruitment to circulation during infection." (PMID 38236896, 2024). "We suggest that upon HMPV infection of human macrophages a mechanism of repressive mark gain additional to the previously identified SETDB2-dependent mechanism is initiated that results in increased H3K27me3 at the IL-1β promoter." (PMID 37435074, 2023). "Moreover, inflammasome gene signatures were attenuated with αCD8 treatment, supporting the notion that CD8+ T cells persisting in the lungs post infection promote chronic inflammasome activation and IL-1β release by macrophages." (PMID 38077031, 2023). "Upon infection, IL-1β is produced by the inflammasome pathway." (PMID 37697284, 2023). "DHAV infection could lead to the different expression of various cytokines in young ducklings; for example, the transcription of IL-1β, IL-2, IL-4, IL-6, IL-8, and IL-10 was highly stimulated after infection." (PMID 37391858, 2023). "IL-1β is a potent proinflammatory cytokine that is crucial for host-defense responses to infection." (PMID 37894054, 2023). "A study found that IL-1β is a significant factor in controlling aggressive pathogens such as hepatitis B and C viruses by activating the expression of the specific immune gene and promoting lymphocyte recruitment to the primary site of infection." (PMID 37208599, 2023). "In our model, the serum levels of IL-1β and IL-23 increased after infection." (PMID 37939119, 2023). "In addition to participating in inflammatory responses and anti-infection defenses, IL-1β and IL-6 also participate in the development and metastasis of some malignant tumors." (PMID 36992837, 2023). "Noteworthy, IL-1β secretion was higher at lower multiplicities of infection." (PMID 38127952, 2023). "IL-1α recruit neutrophils to the infection site while IL-1β is a pro-inflammatory cytokine." (PMID 37756264, 2023). "During acute salmonella-induced mouse peritonitis, resident macrophages secrete the first wave of IL-1β within 1 h post-infection, followed by rapid pyroptosis, and pyroptosis-resistant neutrophils are subsequently recruited as the main source of IL-1β 1–12 h post-infection." (PMID 37090724, 2023). "PTX3 is expressed by various hematopoietic and non-hematopoietic cells in response to microbial moieties and inflammatory cytokines (i.e IL-1β and TNF), and it has been associated with the control of various infections by promoting different anti-microbial mechanisms." (PMID 37222419, 2023). "The induced IL-1β in the rHLJ0504 infection group peaked at 5 dpi and rapidly decreased." (PMID 40303711, 2023). "Thus, we isolated livers of IFNAR-/- and WT mice 30 hours post RVFV cl13 infection and analyzed IL-1β and IL-1RA induction by ELISA." (PMID 37720217, 2023). "Besides, L-arginine supplementation reduced Il-1b during infection, and L-arginine or L-arginine plus putrescine increased Mcp1 at 24h of infection, suggesting that polyamines availability can interfere with cytokine/chemokine production." (PMID 37000792, 2023).
infection (continued). "IL-1β was not generated in any significant amount following infection nor was any increased susceptibility observed in IL-1β nor IL-1βR knockout mice." (PMID 37325809, 2023). "However, NE severity is thought to be a result of excessive production of IL-1β, IL-13 and IL-17 cytokines during infection, a mechanism mediated via Th2 and Th17 cells." (PMID 38164397, 2023). "Moreover, Gasdermin D-deficient mice were susceptible to intraperitoneal bacterial infection, with serious damage to the spleen and reduced secretion of cytokines IL-1β and IL-18 during in vivo infection." (PMID 36761775, 2023). "However, we did not detect any differences in the production of IFN-y, IL-12, IL-22, IL-23, or IL-1β between the control and anti-Gr1 groups after 2 weeks of infection." (PMID 36776848, 2023). "Indeed, we observed a significant decrease in TNF-licensed cell death early during infection, as well as significant attenuation of both IL-1α and IL-1β release, in Casp11-/- BMDMs relative to wild-type controls." (PMID 37279255, 2023). "Because of its inflammatory nature, pyroptosis may be viewed as an altruistic form of cellular sacrifice that is intended to limit infection and spare uninfected neighboring cells through alert signals and inflammatory mediators (IL-1β, IL-18, and DAMPs)." (PMID 36611990, 2023). "TNF-α and IL-1β are known to initiate innate immune response, and mediate the activation, recruitment, and adherence of circulating macrophages and neutrophils to the infection site." (PMID 38053527, 2023). "In addition, pretreatment of BMDMs with MitoQ also significantly inhibited cell death, Caspase-1 activation, and IL-1β secretion in case of ΔfliCΔsiiD or ΔfliCΔsiiD::Vector infection." (PMID 37155697, 2023). "Nevertheless, YH supplementation decreased the concentrations of TNF-α and IL-1β in LPS-challenged piglets, which indicated dietary YH supplementation could decrease the systemic inflammation after LPS infection." (PMID 36932457, 2023). "The changes in bodyweight after infection might depend on the secretion of proinflammatory cytokines, especially IL-1β." (PMID 37063291, 2023). "Although IL-1β may be an attractive therapeutic target, infection in such therapy would be of concern because of the important role of IL-1β in host defense, as reported by the CANTOS." (PMID 36769149, 2023). "Therefore, we measured the expression mRNA levels of interleukin (Il)1b and Il18, which are induced by pyroptosis activation, in BMDMs during infection." (PMID 37457695, 2023). "Infection of THP-1 cells with fdr mutants resulted in increased IL-1β, TNF-α, and IL-4." (PMID 37764917, 2023). "This assay showed similar results, in which IL-1α levels were significantly increased in dual-infected mice compared to S. maltophilia only infection (**P<0.01), and IL-1β levels showed a trending increasing in dual-infected mice compared to S. maltophilia infection." (PMID 36748431, 2023). "This hypothesis is supported by another study that highlighted a strong expression of il-1β and tnf-α early in the infection by A. salmonicida achromogenes." (PMID 36838503, 2023). "Therefore, our results differ from others in the literature that demonstrated that cells trained with a regulatory profile release less IL-1β when trained by natural infection with Plasmodium falciparum and more IL-1Ra when trained with helminth extract." (PMID 37520439, 2023). "Infection with virulent ASFV isolates often results in an exacerbated immune response, associated with elevated serum levels of pro-inflammatory cytokines (IL-1α, IL-1β, IL-6, TNF, CCL2, CCL5 and CXCL10)." (PMID 36680273, 2023). "However, infection by any of these SARS-CoV-2 strains resulted in a mild upregulation of the inflammatory markers including IL-1β, TNF-α, and IL-10 at 3 dpi." (PMID 38257760, 2023). "IL-1α and IL-1β are released in the early stages of infection." (PMID 37112697, 2023).
infection (continued). "The relatively high levels of IL-1β in Rongchang pigs from 2 to 10 days after HuN4 infection might contribute to the persistent increase in body temperature from 2 to 12 dpi and acute lung injury in HuN4-infected Rongchang pigs." (PMID 37920268, 2023). "The AIM2 inflammasome could trigger the innate immune response by producing mature proinflammatory cytokines such as IL-18 and IL-1β, and it might also activate cell necroptosis when facing infections." (PMID 36742336, 2023). "In the present study, we found that the immune response in the intestine of rats in the IEC group heightened by expressing more product of TNF-α and IL-1β when encountering the secondary infection of S.Typhimurium, which was consistent with previous studies about trained immunity." (PMID 37090706, 2023). "Inflammasome activation is an important innate immune activity that regulates at least two host responses that are protective against infections: (i) secretion of the pro-inflammatory cytokines IL-1β and IL-18 and (ii) induction of pyroptosis, a form of cell death that is triggered by inflammation." (PMID 37796003, 2023). "This was performed by collecting and analyzing the culture supernatants of lung explants infected by Fth LVS, Fth LVS ΔiglC, Fth A-660 and F-W12 24 h, 48 h and 72 h post infection to determine the levels of cytokines and chemokines (e.g. IL-1β, IL-6, TNF-α, IL-8, G-CSF, MCP-1, IP-10 and VEGF)." (PMID 37492528, 2023). "While we observed that inhibition of NLRP3 reduced IL-1β secretion during infection with ST, cell death and IL-1β secretion by Xiap−/− cells was still higher than WT cells, suggesting that XIAP inhibits additional cell death pathways to control cell death and IL-1β secretion by APCs." (PMID 37347786, 2023). "The rHLJ0504 group showed the highest IL-1β levels within 7 dpi among the four infection groups." (PMID 40303711, 2023). "The absolute levels of TNF-α, IL-1β and IL-6 in P815 cells measured by ELISA confirmed the results from gene expression with RNA-seq analysis; thus, melatonin significantly reduced inflammatory cytokine levels at 12 h post-infection." (PMID 37200384, 2023). "Considering that STEC infections usually occur at low infective doses, it is dared to speculate that at the beginning of the infection, neutrophils recruited to the gut secrete high IL-1β levels through a mechanism that involves caspase-1 and NSPs activity." (PMID 38127952, 2023). "Interestingly, the frequencies of IFNγ and TNF-producing NP-specific T cells in the BAL were superior to the ones observed after natural infection, confirming the potent adjuvant effect of IL-1β on local TRM formation in pigs." (PMID 37153548, 2023). "Since inflammatory cytokines play important roles in innate immunity, we measured the expression of inflammatory cytokines in the serum of infected mice at day 5 post-infection and observed that in contrast to WT mice the levels of IL-1β were higher but IL-6 were lower in the serum of Xiap−/− mice." (PMID 37347786, 2023). "Compared to the lungs of the mice infected with the wild-type rJS/875 virus, exposure to the rJS/875-MA, rJS/875-PA S49Y+D347G, rJS/875-PB2 S155N, rJS/875-PA S49Y and rJS/875-PA D347G viruses led to significantly higher levels of the cytokines IL-6 and IL-1β on day 3 post-infection." (PMID 37858267, 2023). "There, it serves as a negative regulator of a cytosolic cellular multiprotein complex termed the inflammasome, which mediates the activation of various inflammatory pathways in response to deleterious cellular insults (e.g., infection) and drives the maturation of the IL-1b and IL-18." (PMID 36624531, 2023). "Moreover, the results displayed that increasing TQN levels significantly (p < 0.05) decreased the expression levels of IL-8, TNF-α, IL-6 and IL-1β genes un like the control group at 96 h post-infection with P. multocida." (PMID 38292130, 2023).
infection (continued). "Delta and Omicron infection only marginally altered mRNA expression of IL-1β (Delta vs Mock: p = 0.6114; Omicron vs Mock: p = 0.7534), IL-6 (p = 0.1910; p = 0.2619), IL-18 (p = 0.7755; p = 0.6092), TNF-α (p = 0.9080; p = 0.9405) and IFN-α (p = 0.0612; p = 0.2138)." (PMID 36883057, 2023). "In addition, if we prepared bacteria by first sonicating and then using a 5μmF (so/5μmF), the expression changes resembled so/sp infection, with marked upregulation of Il1b, Il6, Nos2, and Tnf." (PMID 36852737, 2023). "We observed that 10 nM CA prevented the infection-induced pro-IL-1β synthesis in THP-1 cells infected with B. cenocepacia illustrating that results with this inhibitor need to be carefully controlled and interpreted since it can block multiple steps in an inflammasome pathway." (PMID 37787552, 2023). "Moreover, OLE attenuates the inflammatory response to LPS or IL-1β/TNFα stimulation, mimicking the infection and inflammatory status of CF patients, in CFBE and primary nasal epithelial (HNE) cells." (PMID 37443798, 2023). "Like IL‐1β, IL‐1α could initiate infiltration and influx of neutrophils to the lung during IV infection." (PMID 37773712, 2023). "Notably, a gene that encodes glycosylasparaginase, which modulates levels of the host pro-inflammatory cytokine IL-1β, is important for infection in an immunocompetent murine model of fungal disease." (PMID 37790311, 2023). "Regarding direct relations between infection and the three genetic polymorphisms IL1B-31 SNP, IL1B-511 SNP and VNTR, no significance was observed (respective p-values = 0.73, 0.26, 0.59)." (PMID 36838318, 2023). "Furthermore, acute phase proteins such as haptoglobin, cathelicidins, and peptidoglycan recognition protein were recorded at higher rates during infection; similarly, high levels of IL-1β, IL-8, and TNF-α were expressed." (PMID 36899749, 2023). "After observing that IL-1β levels were much lower following infection with F. tularensis LVS than with F. novicida, we investigated whether this discrepancy was due to differences in intracellular bacterial replication." (PMID 37266012, 2023). "In conclusion, our study results show the participation of the NLRP3 inflammasome in the secretion of IL-1β during infection with the NADL cp-BVDV strain; furthermore, we found a possible relationship between the activation of the NLRP3 inflammasome and viral replication." (PMID 37515181, 2023). "However, the levels of IFN-γ, TNF-α, IL-17, and IL-1β were similar in spleens of control and B cell MHCII deficient mice two weeks post-infection." (PMID 37721965, 2023). "However, a combined knockdown of both catalytic subunits of PP2A showed that S205 pyrin phosphorylation was maintained, and there was a significant decrease in IL-1β secretion upon ∆yopM infection." (PMID 37787552, 2023). "As expected, infection significantly induced IL-1β, TNF-α and IL-6 placental secretion." (PMID 36982317, 2023). "The qRT-PCR results show that the transcription levels of the inflammatory factors IL-1β, IL-6, and IL-8 were significantly increased after PCN033 infection, while the transcription levels of the inflammatory factors IL-1β, IL-6, and IL-8 were significantly decreased after treatment with BA." (PMID 37630686, 2023). "Thus, LPS-primed or -unprimed ovine macrophages were infected with BTV-8, and the production of IL-1β was measured in both the lysates and supernatants at different time points post-infection." (PMID 37375491, 2023). "Notably, the recombinant virus reduced anti-inflammatory and pro-inflammatory responses by regulating IFN-γ, TNF-α, and IL-1β secretion after infection." (PMID 37741960, 2023). "Additionally, we assessed the immune response by measuring infection-associated biomarkers (NGAL, IL-8, and IL-1β) within the same urine specimens." (PMID 37627948, 2023). "IL-1β might be the significant driver of the gill pathology developing during the infection with CEV." (PMID 37465154, 2023).
infection (continued). "The activation of IL‐1β in response to infection, mucosal injury, and stress triggers a local mucosal immune response, recruiting neutrophils to the affected site and activating the NF‐κB pathway, which leads to the upregulation of proinflammatory cytokines and chemokines." (PMID 38018571, 2023). "While neutrophils are clearly the main source of IL-1β within the myeloid compartment early in the infection (i.e., 48 h post-inoculation), other cells might take over this role when the amount of infiltrating neutrophils starts to wane over time." (PMID 37958758, 2023). "Additionally, mRNA levels of pyroptosis-related genes (NLRP3, ASC, caspase-1, GSDMD, IL-18, and IL-1β) in the kidneys with W24Δhcp1 infection are considerably lower than in those with WT W24 infection." (PMID 36977062, 2023). "In all groups, IL-1β expression increased after 48 h of infection." (PMID 37047702, 2023). "Moreover, opposed to WT mice, S100A9 KO mice showed substantially increased BAL fluid levels of pro-inflammatory TNF-α and IL-1β and anti-inflammatory IL-10 on day 2 post-infection." (PMID 37467233, 2023). "Furthermore, knockdown of RACK1 significantly inhibited the secretion of IL-1β and TNF-α as well as the transcription of NLRP3 and IL-1β during PmCQ2 infection." (PMID 37684678, 2023). "In zebrafish embryos and larvae, IL1β is induced in response to injury and to various infections." (PMID 36829432, 2023). "Furthermore, we have previously observed significant production of IL-1β from GBS-infected macrophages 24 hours post-infection, which would also be consistent with induction of pyroptosis." (PMID 37928185, 2023). "The present data now reveal the role of TRPA1 as also pleiotropic in mediating protective, homeostatic mechanisms in inflammation and infection because the results indicate an important role for vagus nerve TRPA1 ion channels in activating the thermoregulatory responses to IL-1β." (PMID 36650454, 2023). "infection does not cause ubiquitous increases in IL-1β, malarial hemozoin induces IL-1β secretion via activation of the NLRP3 inflammasome." (PMID 37375100, 2023). "IL-1β is induced during the acute inflammatory process, promoting the up-regulation of adhesion receptors on endothelial and immune cells, which triggers leukocyte infiltration into infection sites." (PMID 38067567, 2023). "We found that CVB3 pre-infection could significantly inhibit the production of IL-1β and the expression of NLRP3 in the small intestine." (PMID 37243164, 2023). "IL1β also regulates infection-driven emergency myelopoiesis via NF-κB and C/ebpβ." (PMID 36829432, 2023). "We hypothesized that the low levels of IFN-β and IL-1β observed upon F. tularensis LVS infection were due to insufficient release of bacterial DNA." (PMID 37266012, 2023). "IL-1β is a potent proinflammatory cytokine which plays a crucial role in the regulation of inflammation and can induce the host defense mechanism during pathogen infection." (PMID 37515077, 2023). "However, we found that A47L-deficient virus was attenuated in a murine macrophage line (ANOVA p = 0.0118) and promoted higher levels of IL-1β release during infection." (PMID 36909515, 2023). "The mRNA levels of interleukin-1β (IL-1β) and tumor necrosis factor alpha (TNF-α) significantly change in response to bacterial infections, indicating their association with other immune-related molecules in fish during infections." (PMID 37569767, 2023). "Our previous study found that infection with meningitic E. coli can significantly increase the expression of chemokines and cytokines, such as IL-6, IL-1β, TNF-α, CXCL3, CXCL2, and C-C motif chemokine ligand (CCL) 2, and some chemokines remain at high levels in the blood and brain for a long time." (PMID 37445610, 2023). "IL-1β is one of the most important modulators of both inflammation and infection." (PMID 37375100, 2023).